MYC (MYC proto-oncogene, bHLH transcription factor)
Diseases named in the same sentence as MYC in open-access papers (continued):
Sharing a sentence is not in itself a finding about the gene and the disease.
cancer (continued). "MYC is elevated in most cancers and several other pathological conditions, and so has been proposed as a drug target for decades." (PMID 37941901, 2023). "The study findings revealed a noteworthy positive correlation between risk scores and key cancer-promoting pathways such as the MTORC1 signaling pathway, MYC TARGETS, and the oxidative phosphorylation signaling pathway." (PMID 38250070, 2023). "The expression of DHODH is regulated by the oncogene MYC, which is significantly upregulated in cancer cells and pluripotent cells." (PMID 36814599, 2023). "CDK12 and CDK13 have gained considerable attention as powerful oncogenic targets in the last years, especially for MYC-driven cancers." (PMID 37202753, 2023). "In cancer, MYC often leads to the increased expression of many genes, some of which are involved in cell proliferation, contributing to cancer formation." (PMID 37007132, 2023). "While most MYC-driven cancer cells are known to share basic alterations in translation and ribosome biogenesis, particularly in MM-derived cell lines, a strong correlation between MYC expression and translation processes has been observed." (PMID 38067212, 2023). "As a grand orchestrator of oncogenic processes of a variety of cancers, the c-MYC gene is frequently activated and/or amplified in HCC." (PMID 36746917, 2023). "For instance, MYC activation in cancer cells can downregulate the expression of major histocompatibility complex (MHC) molecules, impairing antigen presentation and the subsequent activation of T cells." (PMID 37755397, 2023). "In bladder cancer, lncRNA SNHG18 inhibits MYC expression by modulating the ubiquitination–proteasome pathway, resulting in the suppression of cancer cell growth." (PMID 37755396, 2023). "Targeting m6A modifications of oncogenes such as EGFR and MYC can significantly suppress their expression and the proliferation of cancer cells; demethylating metabolic gene PDK4 can reduce its expression and glycolysis of cancer cells." (PMID 36260366, 2023). "Nuclear changes consisted of karyomegaly, marginalization of chromatin, and a single, centralized, and prominent nucleolus that is consistent with other cancers where constitutive MYC activation is present." (PMID 37414763, 2023). "The BRD4 inhibitor (JQ1) competes with BRD4 for binding to acetylated lysines, displacing BRD4 from super-enhancers within the MYC oncogene and reducing MYC expression, resulting in anti-cancer effects in hematopoietic cancers, PDAC and MYCN-driven cancers." (PMID 37755397, 2023). "For example, c-MYC was determined to co-express with mutant IDH1/2 and increase the state of malignancy in MYC overexpressed cancers." (PMID 37110218, 2023). "Because of its ability to inversely regulate the function of RBPs, it is possible to intervene in RBP-influenced cancer progression by targeting and regulating the transcriptional levels and activity of MYC." (PMID 37631029, 2023). "MYC is one of the most frequently dysregulated oncogenes across all human cancers and is well-known to drive poor patient outcomes." (PMID 37130865, 2023). "We recently demonstrated that MYC also contributes to cancer’s escape from immune surveillance by regulating the expression of checkpoint protein ligands (38, –40)." (PMID 36897988, 2023). "To investigate the specificity of EHMT2 inhibition in combination with CFZ, we first verified the regulation of canonical EHMT2 targets such as MYC that has been found to be modulated in multiple type of cancers." (PMID 37190128, 2023). "In contrast, the overexpression of MYC in cancer broadly represses anticancer proteins that promote apoptosis." (PMID 37755397, 2023).
cancer (continued). "Down‐regulated FTO in LC cells promoted the translation of MYC mRNA and increased glycolysis and cancer progression." (PMID 36260366, 2023). "These include well-recognized master regulators of proliferation in the setting of cancer, such as the transcription factor MYC which is under the control of numerous super-enhancers gained in cancer compared to normal tissues." (PMID 37415185, 2023). "Despite its unquestionable contribution to cancer development, MYC has been regarded as undruggable, and there are only a few MYC inhibitors so far." (PMID 37570631, 2023). "Since c‐MYC can act as an RBP to stabilize mRNA in cancer, we used actinomycin D to block the upstream transcription, then to evaluate the mRNA stability using qRT‐PCR assay." (PMID 36208024, 2023). "Although it has been established that MYC signaling is dysregulated in various human cancers, direct targeting MYC remains challenging due to its "undruggable" protein structure." (PMID 37596667, 2023). "Although it has been termed a “most wanted target for cancer treatment”, MYC has remained considered undruggable for a long time." (PMID 36765784, 2023). "The IL-6/STAT3 signaling pathway upregulates factors involved in cancer cell proliferation (MYC, cyclin D1), angiogenesis (VEGFA, PDGF), and apoptosis (Bcl-XL)." (PMID 36720310, 2023). "MYC has also been shown in a few cancer types as one of master transcription factors to control cell phenotypes or identities." (PMID 37345125, 2023). "While c-MYC plays pivotal roles in cell proliferation and cancer development, it also increases the sensitivity to apoptosis in non- and pre-malignant cells." (PMID 36746917, 2023). "To date, such molecular pathways are known that regulate the expression and activity of NAMPT in cancers, such as c-MYC/NAMPT/SIRT1, HMGA1/NAMPT/NAD+, FOXO1/NAMPT, NAMPT/miRNA, SIRT6/SIRT1/NAMPT, C/EBPβ/NAMPT." (PMID 37175631, 2023). "In this study, we found that ISG15-mediated ISGylation of KPNA2 inhibited its ubiquitination degradation, thereby promoting nuclear translocation of c-MYC and maintaining cancer stem-like characteristics in ATC." (PMID 37501099, 2023). "Following knockdown of CCAT1 and MYC, we observed an increase in cancer cell migration and invasion in the transwell assay in Colo205 and HROC277Met2." (PMID 37347737, 2023). "Despite the extensive knowledge about the roles of MYC in carcinogenesis and cultured cancer cells accumulated during the past 4 decades, much less is still known about its roles in normal development and tissue homeostasis." (PMID 37731815, 2023). "Omomyc has served as a key research tool to increase our understanding of MYC biology in different experimental models, including normal and cancer cells and various mouse models of cancer." (PMID 36765784, 2023). "We screened out cuproptosis-related characteristics that predicts poor clinical outcomes and found that the pro-tumoral cuproptosis-based features were putatively enriched in MYC-targets and showed a significantly positive correlation with cancer stemness." (PMID 37353799, 2023). "In turn, MYC has been reported to activate HIF2α transcription by directly binding to its promoter in T cell leukemia and maintaining a pool of cancer stem cells." (PMID 37601651, 2023). "These pathways, as well as the MYC, Notch, and the β-catenin/Wnt signaling pathways, have been identified as being frequently altered in cancer." (PMID 36980704, 2023). "On the other hand, MYC, a proto-oncogene, is often constitutively upregulated in cancers of the cervix, colon, breast, lung, and stomach." (PMID 37509438, 2023). "The proto-oncogene MYC is dysregulated in approximately 70% of human cancers and is overexpressed in MM." (PMID 37635159, 2023). "The precise mechanisms by which the deregulation of the MYC oncoprotein contributes to cancer formation, maintenance and progression are still unclear." (PMID 37755397, 2023).
cancer (continued). "To explore how c-MYC mediates resistance to T/CQ, we examined the cell division cycle, one of the hallmarks of cancer modulated by activated KRAS and c-MYC." (PMID 36719686, 2023). "Dysfunction promotes cancer formation and progression using 2 main mechanisms, i.e., via a cell intrinsic process in which MYC promotes growth of malignant cells and an extrinsic process in which the oncoprotein promotes evasion of host cell immunity." (PMID 37233863, 2023). "MYC overexpression has been noted in addition to CTNNB1 in cancer stem cells, as it is a transcription factor that controls cell growth, differentiation, and cell maintenance." (PMID 37370820, 2023). "MYC is a regulatory transcription factor with essential roles in regulating embryonic stem cell identity and various aspects of cancer biology, including proliferation, growth, metabolism and differentiation." (PMID 37345125, 2023). "Alternatively, KDM2B hinders ribosomal RNA genes, MYC protein, and induces c-Fos ubiquitylation, leading to reduced cancer cell proliferation." (PMID 36975603, 2023). "They establish a link between MYC, lncRNA expression, and cell proliferation, raising the question of the role of the lncRNA–MYC network in cancer." (PMID 37755396, 2023). "We subcutaneously injected these four kinds of cancer cells (SW48 stably expressing Vector + c-MYC WT, NEK8 + c-MYC WT, Vector + c-MYC S405A, NEK8 + c-MYC S405A) into the back of 8-week-old nude mice." (PMID 37596667, 2023). "Overexpression of MYC enhances replication origin activity, which subsequently induces replicative stress leading to DNA damage and checkpoint activation pointing to a critical MYC function in DNA synthesis, which is aberrantly activated in cancer cells." (PMID 36969025, 2023). "MYC functions as a transcription factor that orchestrates the downstream oncogenic signaling networks, which are frequently activated in multiple human cancers, such as breast cancer, liver cancer, colorectal carcinoma, and prostatic neoplasia." (PMID 36830089, 2023). "Several studies reported that MYC inhibition can be effective in cancer treatment, due to the action of a 90-aa polypeptide Omomyc." (PMID 37239035, 2023). "The fact that RUNX3 is frequently hypermethylated in cancer begs the question: will reactivation of the silenced RUNX3 to stem aberrant MYC activity?" (PMID 37400551, 2023). "MYC, a classic oncogene, is significantly correlated with gastric inflammation-cancer transformation." (PMID 37964307, 2023). "Drug sensitivity testing revealed that a KRAS pathway inhibitor exerted strong anti‐cancer effects on the SCCC organoid compared to a MYC inhibitor, which were also confirmed in the xenograft model." (PMID 36691316, 2023). "This well‐validated novel approach allows for the identification of essential MYC‐bound E‐boxes and the regulated target genes in MYC‐dependent cancers." (PMID 37519063, 2023). "In CRCs, c−MYC has been shown to have a role in self−renewal, tumorigenicity, invasion and chemoresistance of cancer stem cells." (PMID 36874096, 2023). "More than 50% of human cancers have MYC signaling dysfunction, which is reportedly correlated with poor overall survival in cancer patients." (PMID 37596667, 2023). "Our study illustrates some findings that are consistent with those in other cancers (e.g., the association between METTL3 and MYC signaling), but we did find many PCa-specific findings that differ from other cancer types." (PMID 37675218, 2023). "Instead, small-molecule inhibitors that target cofactors of MYC, such as histone deacetylase genes, have been developed and are used in the clinic to treat a variety of cancers." (PMID 36977461, 2023). "Histopathologic analyses of hematoxylin-eosin (H&E) stained sections revealed that tumors developed in hep-c-MYC mice were moderately steatohepatitic, contained small droplets of fat in cancer cells (c-MYC)." (PMID 36746917, 2023).
cancer (continued). "It has been noted that cancer cells that are driven by the MYC and KRAS require glutamine for their survival." (PMID 37762231, 2023). "let-7, the first miRNA discovered in humans, involves in many cancer-related genes such as c-MYC, HMGA2, and CCND1." (PMID 37689710, 2023). "Amplified MYC and N-MYC have been shown in multiple cancer models to dampen or ablate molecular clock gene oscillation." (PMID 37639465, 2023). "Second, SOX9 interacts with RUNX2 to induce the transcription of MYC, a known survival factor in OS and many types of cancer." (PMID 37491298, 2023). "The ability of MYC proteins to access chromatin is fundamental to their role in promoting oncogenic gene expression programs in cancer and this function depends on MYC–cofactor interactions." (PMID 37336886, 2023). "This study aimed to understand how the oncogenic transcription factor MYC affects cellular processes contributing to cancer." (PMID 38067212, 2023). "So far, thousands of MYC binding sites and regulated target genes have been identified; however, the question which of them are actually essential for MYC‐dependent cancer cells is still open." (PMID 37519063, 2023). "Our unique, well‐validated tool opens new possibilities to gain novel insights into MYC‐dependent vulnerabilities in cancer cells." (PMID 37519063, 2023). "Given its critical role in so many human cancers, c-MYC is at the center of attention as a potential therapeutic target, but its lack of enzymatic activity has made this task extremely difficult." (PMID 37035206, 2023). "Considering the potential adversary role of MYC activity in the efficacy of a diverse set of cancer therapeutics, MYC status should also be evaluated in the context of other anticancer therapies." (PMID 37642941, 2023). "MYC has been studied extensively in the context of cancer biology, because of its overexpression in malignant tumors and activation of many hallmarks of cancer." (PMID 37495710, 2023). "The transcriptome and bioinformatics analyses revealed that AR-V7 and c-MYC synergistically altered the gene sets involved in various cancer-related biological processes, particularly in lipid and steroid/sterol metabolisms." (PMID 36746917, 2023). "MYC controls the expression of approximately 30% of the human genes and its overexpression is aberrantly in cancer cells." (PMID 38023987, 2023). "These genes have annotations related to cancer, amongst others, and both have functional links to MYC regulation." (PMID 38133254, 2023). "Meanwhile, mounting evidence implicates CDK9, a transcriptional CDK, as a key driver of high-turnover oncogenes, particularly in MYC-dependent cancers." (PMID 36998071, 2023). "Since the MYC‐driven increase in transcription overloads proper pre‐mRNA splicing, the depletion or pharmacological inhibition of core spliceosome components, including SF3B1, is detrimental for MYC‐dependent cancer cells." (PMID 36855776, 2023). "The mutant group exhibited increased expression of cancer-related signals such as MYC targets, E2F targets, DNA repair, oxidative phosphorylation, and G2M checkpoint pathways." (PMID 36707911, 2023). "It is also well-known that the oncogenic upregulation of MYC leads to metabolic reprogramming and promotes the dependence of cancer cells on exogenous glucose and glutamine." (PMID 37443779, 2023). "MYC is one of the most common proto-oncogenes with a wide range of roles in regulating cancer cellular function, including proliferation, differentiation, metabolism, apoptosis, autophagy, aggressiveness, angiogenesis, and immune escape." (PMID 38149239, 2023). "MYC, a transcription factor known for moonlighting as an oncogene in certain cancers, has been reported to repress senescence in several scenarios." (PMID 37706427, 2023). "Seeking novel c-MYC inhibitors represents an urgent demand as c-MYC broadly initiates cancer development." (PMID 37570631, 2023).
cancer (continued). "We obtained a significative enrichment in 70 gene networks mainly related to cancer, immune system, translation, and MYC-related pathways, according to a manual annotation." (PMID 37443350, 2023). "The MYC oncogene is part of the gene superfamily, and its product is commonly activated in human cancers." (PMID 37799727, 2023). "These newly revealed mechanisms urge that more basic structural understanding and regulatory element logic are key to dissect the role of MYC in cancer." (PMID 37601651, 2023). "Among genes with IRESs identified in their 5’UTR, we took an interest in MYC and IGF1R, which are closely associated with cancer stem cell properties." (PMID 37891494, 2023). "Next, DLGAP1-AS2 and YTHDF1 work together to promote the expression of c-MYC mRNA, accelerate the growth of cancer cells and enhance glycolysis." (PMID 37582735, 2023). "Due to these essential roles, the deregulation of c-MYC expression is thought to be involved in many types of cancers." (PMID 37111592, 2023). "In this study, we created a novel tool for the identification of essential MYC‐bound E‐boxes and target genes in MYC‐dependent cancer cells." (PMID 37519063, 2023). "There are many connections between Wnt and PI3K/AKT signaling pathways, including common components relevant to cancer development such as MYC, GSK3, PTEN, and CCND1." (PMID 37856394, 2023). "The gain of function of MYC in cancer cells results from overexpression or from amplification but rarely from mutation." (PMID 38023987, 2023). "These 1,670 genes involved well-established cancer-related genes, including MYC, MYB, BRCA2, ERCC4, and MET for s1 subtype and TERT, BCL2, and SUZ12 for s3 subtype." (PMID 36731467, 2023). "Future work will explore the exact molecular mechanisms by which UBQLN proteins suppress biological processes including proliferation, migration, and cancer progression through the regulation of MYC." (PMID 37444499, 2023). "These proteins have a close association with the regulation of the MYC oncogene, making BET inhibitors effective in MYC-dependent cancers." (PMID 38069407, 2023). "Our results point to a multi-layered regulatory structure that juxtaposes broad-acting factors, such as MYC, with a combination of transcription factors and gene-internal enhancer elements linked with POLR3G upregulation in cancer." (PMID 37894362, 2023). "Previously, difference in the expression of c-MYC and other related proteins have been observed in different stages and subtypes of other cancers." (PMID 36985413, 2023). "The MYC-target gene PLK1 is a well-known cell cycle regulator and oncogene, implicated in the development of several cancer types." (PMID 37183219, 2023). "Transgenic mice overexpressing the p37AUF1 isoform develop spontaneous sarcomas, while cancer-associated transcripts such as CCND1, FOS, and MYC mRNA are significantly increased." (PMID 37631029, 2023). "For example, the use of EpCAM antibody catumaxomab for the treatment of non-small-cell lung cancer shows high efficacy in reducing the expression of MYC and killing cancer cells." (PMID 36966168, 2023). "Thus, MYC-driven cancer cells may be susceptible to AURK inhibitors." (PMID 37422534, 2023).